EPHA2 (EPH receptor A2)
Diseases named in the same sentence as EPHA2 in open-access papers (continued):
Sharing a sentence is not in itself a finding about the gene and the disease.
tumor (continued). "Positive EphA2 immunostaining was predominantly diffusely distributed throughout the cytoplasm of the RCC tumor cells." (PMID 25013485, 2014). "We previously demonstrated that the low expression of favorable NB genes (EFNB2, EFNB3, EPHB6, NTRK1, CD44 and MIZ-1), as well as that of the tumor growth suppressive gene, EPHA2, in NB cell lines was due to epigenetic silencing." (PMID 24190252, 2014). "We conclude that short-shafted Ad5T/41sSK viruses with YSA peptide inserted into the EG, HI or IJ loop selectively transduce EphA2-positive tumor cells, while the long shafted Ad5TS/41sK-IJ-YSA virus showed even stronger, but less selective transduction." (PMID 24760010, 2014). "E2F7 is involved in resistance to therapy, while EPHA2 is overexpressed in a substantial number of tumors and promotes metastasis by stimulating tumor cell migration, invasion, and angiogenesis." (PMID 25122487, 2014). "EphA2 attracts increasing attention as a target for cancer therapy and therefore represents a promising target for tumor-delivery of therapeutic viruses." (PMID 24760010, 2014). "Our results suggest a novel model of molecular complex consisting of CD44 and EphA2 that promote of tumor progression and metastasis." (PMID 24586375, 2014). "It has been found that EphA2 is highly expressed in several types of human malignant tumor cells and in blood vessels, indicating that EphA2 plays a role in tumor development." (PMID 25013485, 2014). "In conclusion, we establish an adenovirus capsid facilitating functional insertion of targeting peptides and a novel adenovirus using the tumor marker EphA2 as receptor with high potential for cancer gene therapy and viral oncolysis." (PMID 24760010, 2014). "A total of 62 archival RCC tumor samples with intact clinicopathological materials were initially tested for EphA2 protein expression by immunohistochemistry and correlated with clinicopathological parameters." (PMID 25013485, 2014). "Nevertheless, inhibition of EPHA1 and EPHA2 resulted in reduced tumor growth and invasiveness in various oncogenic animal models." (PMID 25025847, 2014). "High expression levels of EphA2 are often found in cancer and have been analyzed in tumor cells using a wide range of cell models and clinical specimens, including those of prostate, breast and non-small cell lung cancer." (PMID 25013485, 2014). "EphA2 is dephosphorylated in a wide range of cancer cells and this phenomena seems to correlate with malignancy: tumor cell growth, survival, migration and invasion." (PMID 24086724, 2013). "LMW-PTP is also known to dephosphorylate EphA2, increasing tumor cell growth and differentiation, being the control of the tumorigenic potential of LMW-PTP associated with EphA2 phosphorylation status." (PMID 24086724, 2013). "Recent studies demonstrated that EphA2 is over-expressed in human cancers, and that EphA2 increases tumor invasion and survival, including of patients with CRC." (PMID 24287901, 2013). "Differences in EphA2 or ephrinA1 expression among tumour sites can make chemotherapy against these molecular targets challenging." (PMID 23738943, 2013). "Ephrin-A1 and its primary receptor, EphA2, are not only expressed in multiple malignancies, but also play a vital role in normal angiogenesis and tumor neovascularization." (PMID 24040255, 2013). "It is known that LMW-PTP has the potential to dephosphorylate EphA2 rendering it negatively regulated, which can increase transformation of normal epithelial cells, regulate tumor cell growth, survival, migration and invasion." (PMID 24086724, 2013).
tumor (continued). "High expressions of EphA2, EphA4, and ephrinA1 significantly correlated with variables related to tumour progression, including the depth of invasion, metastatic lymph nodes, pathological stage, and distant metastasis or recurrent disease." (PMID 23738943, 2013). "Histological analysis of tumor sections however, showed considerable higher amounts of necrosis in EphA2-kd cells from both models." (PMID 23951165, 2013). "We found that forced expression of ephrin-A1 down regulated the receptor EphA2 and inhibited cell proliferation and tumor growth in 3D matrigel." (PMID 22824143, 2012). "Recent studies demonstrate the additional involvement of ephrin-A1 and EphA2 in postnatal and tumor angiogenesis." (PMID 22363788, 2012). "The effects can be reversed by ligand stimulation, which triggers the intrinsic tumor suppressive signaling pathways of EphA2 including inhibition of PI3/Akt and Ras/ERK pathways." (PMID 22916121, 2012). "Receptor EphA2 and its ligand ephrin-A1 form an important cell communication system with its functional role in cell-cell interaction and tumor growth." (PMID 22824143, 2012). "In contrast NSCLC cells transfected with pcDNA-EphA2 showed aggressive tumor growth which was significantly larger in size as compared to tumors grown after silencing the EphA2 with siRNA." (PMID 22824143, 2012). "It is plausible that over expression of receptor EphA2 promotes claudin-2 which in turn enhances tumor colonization of A549 cells." (PMID 22824143, 2012). "We demonstrate that activation of receptor EphA2 with ephrin-A1 induced cdx-2 expression and inhibited tumor formation." (PMID 22824143, 2012). "Our study suggests that EphA2 signaling up-regulates the expression of the TJ-protein claudin-2 that plays an important role in promoting cell proliferation and tumor growth in NSCLC cells." (PMID 22824143, 2012). "Overall, these results suggest that ephrin-A1 plays an important role in tumor progression, but the exact function is complex, cell-type dependent and most likely relies on many factors, including its preferred receptor EphA2." (PMID 22853000, 2012). "As a ligand-mimicking agonist for EphA2, doxazosin is expected to activate EphA2 on tumor cells and repulse migrating tumor cells in vitro." (PMID 22916121, 2012). "Other tumor suppressor functions of EphA2 are also activated upon ligand-induced EphA2 activation, including inactivation of the Ras/ERK pathway." (PMID 22916121, 2012). "Whereas, the forced expression of ephrin-A1 induced tumor suppressive signals via downregulation and degradation EphA2 and inhibited the oncogenic singling pathway in NSCLC." (PMID 22824143, 2012). "The major finding of our present study is that receptor EphA2 is over expressed in NSCLC cell lines which promotes tumor growth." (PMID 22824143, 2012). "The novel finding of our present study is that receptor EphA2 mediated the enhanced induction of functionally altered claudin-2 via down-regulation of tumor suppressor gene expression cdx-2 in NSCLC cells." (PMID 22824143, 2012). "In turn, the over expression of claudin-2 along with EphA2 promotes A549 cell proliferation and tumor growth." (PMID 22824143, 2012). "Ephrin-A1 is supposed to act as a tumor suppressor through its preferred receptor EphA2 which is overexpressed in NSCLC." (PMID 22853000, 2012). "In the present study we noted exaggerated tumor colonies formation when EphA2 was over expressed in A549 cells." (PMID 22824143, 2012). "Another gene directly regulated by Hoxa1, EphA2, has also been reported to transform mammary epithelial cells and to promote tumor formation in vivo." (PMID 21957483, 2011). "In this regard, signaling of ephrinA1 and tumor cell-specific EphA2 suppresses processes like growth and migration, whereas interaction of ephrinA1 with ECs-specific EphA2 seems to stimulate these same effects." (PMID 20224755, 2010). "The first ones were directed against EphA2 and showed a significant inhibition of tumor growth in vitro." (PMID 20224755, 2010).
tumor (continued). "One feature that appears to distinguish oncogenic EPHA2 from the tumor suppressive form is its cellular localization." (PMID 20979646, 2010). "Blocking EphA receptor signaling using soluble EphA2-Fc and EphA3-Fc receptors decreased tumor vascular density, tumor volume and cell proliferation in vivo, suggesting that the soluble receptors inhibited blood vessel recruitment by the tumor." (PMID 20224755, 2010). "Use of an agonistic antibody of EphA2 (EA5) in combination with paclitaxel substantially reduced tumor growth in an ovarian cancer model, including a paclitaxel-resistant model." (PMID 20072701, 2010). "They found both ephrinA1 and EphA2 expressed in tumor cells and endothelial cells in these xenografts, and also in vasculature and tumor cells of surgically removed human cancers." (PMID 20224755, 2010). "Not only tumor cells but also tumor endothelium expresses a high level of EphA2, suggesting a role for the receptor within the tumor cell and in the surrounding tumor microenvironment." (PMID 20130824, 2009). "The observed inhibitory effect on tumor vasculature was in agreement with previous studies where a soluble EphA2/Fc receptor was used as a receptor antagonist to block endogenous EphA2 signaling." (PMID 20130824, 2009). "In light of the role of EphA2 in angiogenesis, the impact of IgG25 and IgG28 administration on tumor vascularization was also monitored." (PMID 20130824, 2009). "In fact a significant impact on tumor growth has also been reported by siRNA-mediated knock down of EphA2 expression." (PMID 20130824, 2009). "Monoclonal antibodies to down modulate EphA2 and siRNA studies were reported to inhibit the growth of human breast and lung tumor xenografts in nude mice and tumor angiogenesis and metastatic progression." (PMID 18714348, 2008). "In line with that pathophysiology, several Ephs and ephrins, including EphA1, EphA2, EphA3, EphA4, EphB2, EphB3, and ephrin-A1, are overexpressed in a variety of tumors, and exhibit mostly tumor-promoting properties." (PMID 18648668, 2008). "Ephrin A5 preferentially interacts with EphA2, A3, A5, A6, A7 and B2, of which only EphA2 and EphB2 were expressed to any significant degree in the tested normal or tumor samples." (PMID 16737551, 2006). "Increased tumour cell staining of EPHA2 and Ephrin-A1 was found in 23 and 72%, respectively, in ID1 strong cases, compared with 9 and 47% in ID1 weak cases." (PMID 16189525, 2005). "In this regard, we have identified five human leukocyte antigen (HLA)-A2 binding and three HLA-DR4-binding peptides derived from EphA2 that are capable of inducing specific, tumor-reactive CD8+ or CD4+ T-cell responses, respectively." (PMID 15563374, 2004). "Thus, we set out to determine if the host immune system plays a role in EphA2-mediated KPL tumor growth in vivo." (PMID 40867322, 2025). "In contrast, Δ Ecto and EphA2-85 CAR-T cells exhibited a trend of increasing tumor size." (PMID 40181964, 2025). "Investigating EphA2’s impact on the host immune system may advance our understanding of tumor immune evasion and the consequences of targeting EphA2 on the tumor microenvironment." (PMID 40867322, 2025). "Our studies identify a novel mechanism that contributes to EphA2’s pro-tumor effect in NSCLC." (PMID 40867322, 2025). "Although the roles of EphA2 within the cancer cell and tumor endothelium are well studied, their impact on the tumor immune microenvironment is largely unknown." (PMID 40867322, 2025). "Interestingly, a Wnt5a∧High/EphA2∧Low GSC subpopulation was more tumorigenic than Wnt5a∧Low/EphA2∧High cells, and combined inhibition of Wnt5a and EphA2 drastically reduced invasion and tumor growth." (PMID 41200151, 2025). "Furthermore, tyrosine phosphorylation-independent regulation of EphA2 mediates tumor aggressiveness, including metastasis, invasion, and poor prognosis." (PMID 40065768, 2025). "Knockdown of EphA2 or treatment with ephrinA1-Fc impairs self-renewal and tumor growth." (PMID 41200151, 2025).
tumor (continued). "Additionally, high tumor-to-pancreas ratios across all xenografts confirmed that [68Ga]AJ201 detects variable EphA2 levels in PDAC in vivo." (PMID 40225586, 2025). "We found that EphA2 overexpression contributes to increased myeloid cell populations and decreased T-cell populations, as well as decreased T-cell activation, suggesting it creates an immune suppressive environment that allows tumor cells to grow." (PMID 40867322, 2025). "EphA2 has been studied extensively in tumor development and progression." (PMID 40236294, 2025). "Next, we investigated whether targeting EphA2 in tumors would control tumor growth in a preclinical model of PDAC." (PMID 40225586, 2025). "In another study, a tumor-targeting ligand (EphA2) was conjugated to microspheres blended with PCL and PLGA, demonstrating excellent therapeutic efficacy by successfully inhibiting local tumor regrowth in triple-negative breast cancer through prolonged drug release for more than 90 days." (PMID 41155989, 2025). "The results of the TUNEL assay demonstrated that the mean apoptotic index of tumor cells was significantly higher in EphA2-knockdown RCC tissues than in the control RCC tissues on day 18 of tumor maintenance in the orthotopic RCC kidney (7.0 ± 2.3% vs. 1.6 ± 0.9%, p = 0.021)." (PMID 41440001, 2025). "This would suggest that EphA2 is signaling differently in these two tumor types, or at least in these two particular models, and may explain why the immune phenotypes differ." (PMID 40867322, 2025). "Similar effects are achieved using ephrinA5-Fc or EphA2-Fc, reinforcing its tumor-suppressive role." (PMID 41200151, 2025). "We propose that EphA2 in the tumor cell upregulates the expression of chemokines in the tumor milieu that recruit circulating monocytes into the tumor, where they differentiate into macrophages and are co-opted to serve tumor-promoting functions as polarized M2 TAMs." (PMID 40867322, 2025). "Studies have demonstrated that combining EphA2-targeted therapies with inhibitors of the DNA damage response, such as Wee1 kinase inhibitors, can enhance therapeutic efficacy by inducing apoptosis and reducing tumor cell viability." (PMID 41583426, 2025). "EphA2 overexpression in the cancer cell may directly upregulate myeloid-attracting chemokine expression in the tumor cells, but it may also indirectly affect expression in other stromal cells that can secrete these chemoattractants." (PMID 40867322, 2025). "Additionally, the combination of EphA2 inhibitors with histone deacetylase inhibitors has been shown to downregulate survival pathways and reduce tumor burden, highlighting the promise of multitargeted approaches in endometrial cancer treatment." (PMID 41583426, 2025). "Within GBM tumor-propagating cells (TPCs), EphA2 expression correlates with higher tumorigenicity." (PMID 41200151, 2025). "We next determined if EphA2 overexpression could impact tumor growth in vivo using two different models: subcutaneous implantation and tail vein injection for generation of lung tumors in immunocompetent, wild-type C57BL/6 mice." (PMID 40867322, 2025). "Advancing EphA2‐CAR‐NK cell therapies toward clinical application will require further in vivo preclinical studies using advanced animal models that better mimic the human tumour microenvironment and its immunosuppressive challenges." (PMID 39763064, 2025). "In addition, tumor-specific EphA2 overexpression led to increased PD-1 expression in both CD4+ and CD8+ T cells, while CTLA-4 levels were unchanged." (PMID 40867322, 2025). "Notably, persistence of EphA2 signaling clusters upon internalization in turn regulates metastasis potential in some tumor models." (PMID 40411427, 2025). "Given previous work has shown that EphA2 can play both tumor-promoting and -suppressing roles, we investigated whether EphA2 overexpression in our murine NSCLC cell lines impacted cell viability and tumor growth." (PMID 40867322, 2025).
tumor (continued). "One promising target is EphA2 (Ephrin receptor A2), which is highly expressed in PDAC and implicated in cancer progression through its roles in cell adhesion, migration, proliferation, and the maintenance of the tumor's immune suppressive microenvironment." (PMID 40225586, 2025). "In addition, EphA2-knockdown cells exhibited a decreased tumour-initiating frequency and tumour volume in vivo." (PMID 38916835, 2024). "Moreover, in vivo xenografts demonstrated that EphA2 overexpression in shTGFBI mice (shTGFBI+EphA2-OE) accelerated tumor growth, as indicated by HE staining, and led to decreased mouse survival." (PMID 39346536, 2024). "This suggests that more EphA2 is released from the cell surface as the tumor size increases." (PMID 39766211, 2024). "EphA2 was strongly and diffusely expressed in >50% of cells in tumor and control brain samples." (PMID 39473196, 2024). "This functional connection with ATM losses could elucidate the observed ANT relationship EPHA2 and ATM mutations across tumor types." (PMID 39160568, 2024). "Furthermore, suppression of tumor initiation against EphA2 using CRISPR-Cas9 mediated increased overall mouse survival." (PMID 39839790, 2024). "In EWS tumor, EphA2 interacts with CAV1 through a caveolin binding motif (WSYGIVMW)." (PMID 39596256, 2024). "Conversely, inhibiting EphA2 expression using small interfering RNA (siRNA) has been shown to impede the malignant progression of pancreatic, ovarian, and mesothelioma tumor cell lines, underscoring the pivotal role of EphA2 in tumor development." (PMID 38811954, 2024). "In addition, as in other tumors, EphA2 exhibits angiogenic potential in CRC by contributing to neovascularization or vasculogenic mimicry in the tumor microenvironment (TME) of these tumors." (PMID 38651144, 2024). "Subsequently, using a subcutaneous xenograft mouse tumour model established by injecting SCC9 cells divided into NC, shEphA2, shEphA2 + OE-YAP, and shEphA2 + OE-KLF4 groups, we found that EphA2 knockdown reduced the tumour volume and weight, while YAP or KLF4 overexpression reversed these effects." (PMID 38916835, 2024). "This converts EphA2 from a tumor suppressor to an oncogene (44, –46)." (PMID 38683990, 2024). "EphA2 also promotes the proliferation and migration of malignant tumor cells." (PMID 38267913, 2024). "In addition, the SASP induces cell plasticity and stemness, and sEVs from senescent cells can promote tumor cell proliferation through EphA2." (PMID 38698420, 2024). "Non-canonical EphA2 signaling has been associated with driving melanoma cell phenotypes, enhanced levels of aggression in gliomas, tumor progression in several cancers, metastasis, and EMT." (PMID 39466050, 2024). "Interestingly, this effect was even more pronounced in Eva xenografts, as both tumor initiation and growth were suppressed by EphA2 silencing." (PMID 39056783, 2024). "EPHA2 increased expression leads to decreased tumor infiltration by CD8 T-cells." (PMID 38476371, 2024). "Downregulation of EphA2 or EphB4 using small interfering RNAs (siRNAs) or antisense oligonucleotides has demonstrated significant impact on cancer cell malignancy in culture and has shown efficacy in inhibiting tumor growth in various mouse cancer models." (PMID 38811954, 2024). "EPHA2 has been demonstrated to regulate multiple cellular processes in embryonic development, angiogenesis, and tumor occurrence through EphA2-ephrin A1 signaling transduction, including proliferation, survival, migration, morphology, cell repulsion, and adhesion." (PMID 38773226, 2024). "Elevated expression of EPHA2 has been detected in various tumor tissues." (PMID 38531846, 2024). "Notably, EphA1 and EphA2 exhibited heightened expression in the C1 and C2 subtypes, indicating a plausible involvement in tumor promotion." (PMID 38952552, 2024). "DCs loaded with EphA2 peptide have been found to induce immune responses and reduce tumor burden." (PMID 38811954, 2024).